IL1B (interleukin 1 beta)
Diseases named in the same sentence as IL1B in open-access papers (continued):
Sharing a sentence is not in itself a finding about the gene and the disease.
melanoma (continued). "As we showed, melanoma exosome-delivered miR-125b-5p reinforces the activation of M1 macrophages through the induction of CCL1, CCL2, and IL-1β expression, thus contributing to myeloid cell recruitment and cancer-associated inflammation." (PMID 32079286, 2020). "It appears also of great interest that in WM266-4 melanoma cells the SFN/FB combination inhibited inflammasome formation (i.e., NLRP3, cleaved caspase-1 and ASC expression) and IL-1β production significantly more than each single compound." (PMID 32486135, 2020). "An alternative mechanism explaining BRAFi treatment-induced tolerance, in melanoma, is represented by a cytokine-signaling network involving TAM-derived IL-1β and CAFs-derived CXCR2 ligands." (PMID 32825489, 2020). "Single-molecule analysis of serum expression identified IL-1b, IL-6, IP-10, PDGF-BB, and RANTES differently expressed in melanoma (p < 0.05)." (PMID 33302400, 2020). "Using qRT-PCR we observed an increased expression of IL-1β, CCL1, CCL2, and CD80 in transfected M1 macrophages, similarly to in M1 macrophages co-cultured with melanoma cells or treated with melanoma-derived exosomes." (PMID 32079286, 2020). "Together, our results demonstrate that IL-1β treatment promotes the stem cell-like capabilities of both HNSCC and melanoma cells." (PMID 32547321, 2020). "The SFN/FB combination inhibited melanoma cell migration in vitro, MMP-1, -2, -3, and -9 production, inflammasome activation and IL-1β secretion more efficiently than each individual compound did." (PMID 32486135, 2020). "When cultured in the presence of IL-1β, Th17 cells express high levels of IFN-γ and exhibit enhanced antitumor effect in mice with melanoma." (PMID 30800130, 2019). "In conclusion, IL-1β mediated COX-2 expression and prostaglandin E2 release, in which NF-κB p65 and p105 functioned as transcriptional factors in canine melanoma cells." (PMID 30562372, 2018). "Next, we examined the involvement of NF-κB signaling in IL-1β-mediated prostaglandin E2 release and COX-2 mRNA expression in canine melanoma cells by using NF-κB inhibitors." (PMID 30562372, 2018). "In the present study, cytokines secretion, evaluated by Luminex technology, showed different levels of pro-inflammatory cytokines like IL-1β, IL-8 and TNF both in melanoma cell lysates and in supernatants." (PMID 30591049, 2018). "This is in-line with our finding that melanoma-conditioned TAMs displayed M2-like phenotype, including increased CD163 protein expression and TNF-α low, IL-1β low, TGF-β high and IL-10 high phenotype." (PMID 30459241, 2018). "IL1B has been shown to enhance the invasiveness of TNBC cells in vitro and in IL1B knockout mice, IL1B was essential for the invasiveness of B16 melanoma xenografts." (PMID 28143606, 2017). "Apte and his colleagues injected melanoma cells into C57BL/6 wild-type, Il1a, and Il1b knockout mice, respectively." (PMID 28360909, 2017). "First, we confirmed the presence of an inflammatory microenvironment in melanoma and detected increased IL1A and IL1B expression in stage-III and stage-IV melanoma patient samples." (PMID 28450382, 2017). "As IL-1β and IL-6 are bona fide TNF-α targets, this delineates a potent feed-forward mechanism of melanoma dedifferentiation instigated by TNF-α." (PMID 26530832, 2015). "Furthermore, c-Jun engagement by TNF-α and other cytokines such as IL-1β and IL-6 is critical to trigger inflammation-induced dedifferentiation of melanoma cells and the progressive acquisition of a pro-inflammatory cell state that characterizes MITFlow/c-Junhigh melanoma cell lines and tumours." (PMID 26530832, 2015). "Next, we confirmed these findings by qRT–PCR for the TNF-α responsive genes IL1B and IL6 using independent MITF siRNAs in MZ7 and two other MITFhigh melanoma cell lines, Ma-Mel-15 (MM15) and Ma-Mel-27 (MM27), respectively." (PMID 26530832, 2015).
melanoma (continued). "The model included melanoma cell signals (VCAM-1 ligand, IL-8, and IL-1β) as well as downstream p38 MAPK, Src, PKC, and MLC signaling pathways within the endothelium." (PMID 25225982, 2014). "In vitro, secreted factors from the melanoma cell line induced IL-18-dependent upregulation of VCAM-1 on hepatic sinusoidal endothelial cells, as well as IL-1β secretion." (PMID 24795727, 2014). "Studies on human endothelial cells and other melanomas report that HLA-E can be shed upon treatment with IFN-γ, IL-1β or TNF-α." (PMID 24236107, 2013). "Serum cytokine levels (including IL-1α, IL-1β, IL-2, IL-6, IL-10, IL-12, TNF-α, IFN-γ and IFN-α) were lower in A375 melanoma bearing mice treated with G3139 + VRP + ACV + PAC.PBP + DNR + X rays than in controls treated with physiological saline." (PMID 22233801, 2012). "However, as it has been reported that tumor cell lines, including melanoma cell lines, can express IL-1R1, we can postulate that IL-1β, which is known to promote matrix metalloproteinase expression, could increase the production of sHLA-E by IL-1R1 expressing tumor cells." (PMID 21712991, 2011). "The specific effects of IL-1ra on tumor proliferation and metastases via the transduction of human IL-1ra into two human melanoma cell lines (PMEL and SMEL) with differential IL-1β expression (low vs. high, respectively) were illustrated." (PMID 17096856, 2006). "A deeper mechanistic understanding is needed, specifically, comprehensive assessment of inflammatory cytokines (IL-1β/6/8, TNF-α), ROS scavenging efficacy, and molecular profiling (qPCR/Western blot) will be incorporated to validate the anti-melanoma mechanisms of pYEEIE-RELNs-DOX." (PMID 40792208, 2025). "Additionally, human melanoma cells constitutively express and activate NLRP3, leading to autoinflammation through caspase-1 activity and the production of biologically active IL-1β." (PMID 41017127, 2025). "However, in melanoma cell lines LB2259-MEL and CP50-MEL treated with IL-1β, IL-1β might reduce the expression of MITF through the NF-κB and JNK pathways, and this reduction is associated with the expression of the IL-1 receptor type I (IL-1RI) gene in melanoma cells." (PMID 39689154, 2025). "Future study may focus on the combinatory treat of vemurafenib-resistant melanoma by targeting both of LINC01198 and IL-1β may also endorse promising for improving cancer treatment efficacy and tackle down vemurafenib resistance." (PMID 41145465, 2025). "However, IRF7 knockdown with small interfering RNA (siRNA) significantly inhibited these inflammatory factors (IL‐1β, TNF‐α, IFN‐α, and IFN‐β), CD80 and CD86 in macrophages co‐cultured with irradiated melanoma cells." (PMID 38286661, 2024). "In addition, the presence of IL-1β can upregulate the expression of TYR and TRP-1 in mouse melanomas." (PMID 39335872, 2024). "V. cinerea extract also significantly inhibited lung tumor formation (by 78.8%) in B16F-10 melanoma cells by suppressing the production and expression of proinflammatory cytokines such as TNF-α, IL-1β, IL-6, and granulocyte-macrophage colony-stimulating factor (GM-CSF)." (PMID 38732642, 2024). "Similarly, in B16F10 melanoma, the inhibition of NLRP3 reduced tumor growth and synergized with checkpoint blockade therapy, suggesting that inflammasome-derived IL-1β promotes tumorigenesis." (PMID 38391959, 2024). "Contrary to many reports, melanoma cells are not the main source of IL‐1β due to the absence of inflammasome components." (PMID 38775220, 2024). "In TME, IL‐1β activating suppressor of mothers against decapentaplegic/DNA‐binding 1 protein inhibitor, the Smad/ID1 signaling pathway ensures maintenance of the stemness traits of melanoma cells, thus acting as a promoter of tumor relapse and metastasis." (PMID 38775220, 2024). "In children with ASD, an increase in the NLRP3 inflammasome and another inflammasome complex, absent in melanoma 2, and accordingly the production of IL-1β and IL-18 inflammatory cytokines were observed." (PMID 38026692, 2023).
melanoma (continued). "Of note, we have also tested the levels of other cytokines (i.e. IL6, TNF-α and IL1β) in THP-1 cells exposed to CM coming from melanoma cells and we have not observed any significant modulation." (PMID 36418472, 2023). "Since we have investigated both primary and metastatic cell lines, these data suggest that there is no meaningful endogenous IL‐1β secretion by melanoma cell lines regardless of origin." (PMID 36707938, 2023). "By setting the number of shear-resistantly arrested melanoma cells to 100% for both conditions, the TNF-α-stimulated and the IL-1β-stimulated pMBMECs, we revealed an adhesion-independent increased melanoma cell intercalation into the barrier-compromised IL-1β-stimulated pMBMECs." (PMID 37894438, 2023). "Its growth inhibitory effects are mediated by cell cycle G1-arrest associated with DNA damage and induction of apoptosis while other studies on murine melanoma cells showed that piperine treatment significantly reduced proinflammatory cytokines such as TNF-α, IL-1β and IL-6." (PMID 36768978, 2023). "The immunomodulatory MXs effects have also been confirmed by more recent studies involving human melanoma initiating cells (MICs), showing caffeine’s ability to induce a significant reduction of MIP-1α, MIP-1β, IL-1β, IP-10 and RANTES secretion by MICs within the conditioned media." (PMID 36768978, 2023). "Intraperitoneal administration of andrographolide significantly inhibited the B16-F10 melanoma cell line-induced capillary formation in C57BL/6 mice and reduced the levels of pro-inflammatory cytokines, such as IL-1β, IL-6, TNF-α and GM-CSF, and serum NO level." (PMID 36768978, 2023). "Furthermore, recent research has indicated that IL-1β partially mediates UVB-induced melanogenesis by upregulating the expression of TYR and TRP1 in melanoma B16 cells." (PMID 37781032, 2023). "Further evidence demonstrates that IL-1β does not seem to be controlled via an autocrine feedback loop, as the use of exogenous IL-1β does not recover the cytokine expression in melanoma cells." (PMID 37627054, 2023). "Most melanoma cells silence the expression of one or more inflammasome components and do not produce IL-1β by themselves; rather, they induce IL-1β production from TAMs by releasing endogenous danger signals." (PMID 37046775, 2023). "However, the cell culture supernatants from A375 and RPMI-7951 melanoma cell lines contain TGF-β and IL-1β and also profoundly increase the production of IL-1β and IL-33 in MCs." (PMID 35669782, 2022). "Though Nivolumab did not significantly alter serum cytokine profiles, in melanoma patients we observed a deviation from the physiological range for 7 out 18 cytokines tested: IL-1β, IL-6, CCL2, CXCL8, VEGF, IL-5 and IL-13." (PMID 35173725, 2022). "When canine melanoma cells were stimulated with IL-1β at the concentration of 100 pM for 0–48 h, the activity of MMP-3 in the culture media supernatant was increased, which implies IL-1β-stimulated MMP-3 release." (PMID 36445856, 2022). "IL-1β was demonstrated to mediate MMP-3 expression and release in melanoma cells." (PMID 36445856, 2022). "In various malignant TMEs, including those fostered by surrounding melanoma, immunosuppressive cytokines, such as TGF-β, and the pro-inflammatory mediators of the IL-1 family, IL-1β and IL-33, have emerged as key facilitators of tumor growth, angiogenesis, and modulators of local immune responses." (PMID 35669782, 2022). "SARM1 inhibits the activation of Klebsiella-induced absent in melanoma 2 inflammasome to limit IL-1β production, suppressing further inflammation." (PMID 35947948, 2022). "Metastatic melanoma cell lines do not secrete IL-1β; rather, they promote IL-1β production from macrophages in mice." (PMID 36077992, 2022). "Lastly, IL-1β can upregulate HIF1α, known to inhibit MITF and increase melanoma invasiveness." (PMID 34604096, 2021).
melanoma (continued). "Interleukin-1-α (IL-1α) and interleukin-1-β (IL-1β) upregulate MC1R mRNA in normal human melanocytes, while TNF-α and TGF-β, that potently repress melanogenesis in melanoma cells, moderately downregulate MC1R expression in normal melanocytes and mouse melanoma cells." (PMID 34356109, 2021). "In comparison to the levels of IL-1β typically generated via NLRP3 activation in myeloid cell populations, the levels of IL-1β secretion via the tumor-intrinsic NLRP3 pathway in both murine melanoma models and in human melanoma cell lines are minimal." (PMID 34638239, 2021). "The analysis revealed that expression of baseline NLRP3/IL-1β levels do not consistently correlate with the IFN-γ signature, which have been positively linked to anti–PD-1 efficacy in melanoma patients." (PMID 33649199, 2021). "First, this study tested whether IL1β-mRNA was detected in lung TCM prepared by the coculture of lung specimens with various TCMs using LLC, E0771, or B16 melanoma cells." (PMID 34135341, 2021). "The critical role of IL-1β is brought to light in melanoma cells, as the late-stage human melanoma actively secretes IL-1β without exogenous stimulation." (PMID 33613533, 2020). "In this study, our data indicate the IL-1β stimulation could enhance the stemness of HNSCC and melanoma cells through activating Smad1/5/8 and ID1 signaling pathway." (PMID 32547321, 2020). "Thus, in our future study, we will determine the therapeutical efficacy of IL-1β neutralization in HNSCC and melanoma." (PMID 32547321, 2020). "Since the inflammatory microenvironment provides melanoma tolerance to targeted therapy, targeting NLRP1/IL-1β may be an important strategy to improve MAPK inhibitor efficacy." (PMID 33396632, 2020). "In our subcutaneous B16 melanoma model, IL-1β injections alone did not significantly alter the growth of established tumors or mouse mortality." (PMID 31405895, 2019). "Experimental evidence suggested that resveratrol-treated ATC cells showed remarkable growth arrest and extensive apoptosis, and that it was able to reduce IL-1β expression in either in vivo or ex vivo human noncancerous models or melanoma cells." (PMID 31174324, 2019). "Similarly, a previous study revealed that in the blood of melanoma cell-infiltrated livers, TNF-α and IL-1β were inhibited, and IL-18 augmentation was prevented by treatment of resveratrol." (PMID 30670927, 2018). "S. mutans induced IL-1β secretion via caspase-1 activation, and S. mutans-induced IL-1β secretion required absent in melanoma (AIM2), NLR family pyrin domain-containing 3 (NLRP3) and NLR family CARD domain-containing 4 (NLRC4) inflammasome activation." (PMID 30078841, 2018). "In case of IL-1β-/- mice, no vascularization of Matrigel plugs containing B16 melanoma cells occurred." (PMID 30042333, 2018). "This suggests that, under normal growth conditions, melanoma cells do not produce significant amounts of precleaved IL-1β, and yet, they have the capacity to do so when stressed." (PMID 28450382, 2017). "However, in contrast to TNF, which has been shown to directly prevent melanoma cell death in the presence of BRAF signaling inhibition, IL-1β cannot prevent cell death when BRAF signaling is inhibited." (PMID 28450382, 2017). "Although we found IL1β levels increased in supernatants from M2-BCG, blocking of IL1β did not prevent M2-BCG conditioned medium from increasing GrB release in our TILs-melanoma short-term cocultures (not shown)." (PMID 28848560, 2017). "Thus, we studied the pro-inflammatory pathway activity by measuring the expression of TNF-α inducible genes IL1-α, IL1-β, IL6 and IL8 across melanoma cell lines pairs." (PMID 27175588, 2016). "In conclusion, the present study has shown that macrophage IL-1β and TNF-α may promote VEGF-C expression in TAMs and may have a role in melanoma lymph node colonization." (PMID 25120672, 2014).
melanoma (continued). "In the present study, TNF-α and IL-1β were found to cooperate to promote the colonization of peritoneal lymph nodes by murine melanoma cells, when they were used at a non-toxic dose." (PMID 25120672, 2014). "The involvement of inflammation in melanoma, the most malignant type of skin cancer, is indicated by the upregulation of inflammatory cytokines including IL-6, IL-8, CCL5, and IL-1β, all of which can be regulated by active IL-1β." (PMID 24474192, 2014). "Lipopolysaccharides can stimulate normal human melanocytes to produce IL-1β, TNFα, IL-6, IL-8, CCL2, CCl3, and CCL5, and chemotherapy of melanoma-bearing mice results in enhanced expression of CCL5 and the CXCR3 ligands CXCL9, CXCL10, and CXCl11 by tumor cells." (PMID 22745913, 2012). "They demonstrated that IL-1α/IL-1β knockout mice failed to develop solid tumors following injection of melanoma cells and exhibited significantly improved survival compared to the wild-type animals, which died due to lung metastases." (PMID 17096856, 2006). "Our results on elevated neutrophil velocities in ET are completely in line with the hypothesis that JAK V617F can trigger the Aim2 (absent in melanoma 2) inflammasome and lead to IL-1β generation." (PMID 41465385, 2025). "Moreover, in human WM115 and WM266-4 melanoma cells, the combination of SFN (5 and 10 μM) and Fernblock® XP (FB) hindered melanoma cell migration in vitro and curbed the production of MMP-1, -2, -3, and -9, inflammasome activation, and IL-1β secretion." (PMID 38671854, 2024). "The combinatory therapy of immunostimulatory cytokines IL-1β, IL-18, or IL-12 with GSDMD-based pyroptosis while not causing systemic adverse effects generates a robust antitumor response, ultimately leading to long-term remission in mouse melanoma model." (PMID 39737979, 2024). "It implies that ZBSO may suppress melanoma independently of TNF-α and IL-1β pathways." (PMID 37081962, 2023). "However, IL-1β failed to mediate the expression of MMP-3 mRNA in p65/RelA-knockdown melanoma cells but not in p105-knockdown cells." (PMID 36445856, 2022). "Thus, IL-1β mediates the MMP-3 expression and release in canine melanoma cells." (PMID 36445856, 2022). "Accordingly, in the mouse melanoma model B16F10, it has been recently shown that IL-1β administration to the host may exert adjuvant effects on the expansion and cytotoxic capacities of T cells in patients that are irresponsive (or poorly responders) to adoptive cell therapies (ACTs)." (PMID 36144933, 2022). "Thus, the fact that multiple cytokines synergize in modulating C3 expression would explain why TGF-β, IL-33, and IL-1β activity blockade did not fully inhibit the expression of C3 in MCs treated with melanoma cell culture supernatants." (PMID 35669782, 2022). "Moreover, knockdown of ID1 could abrogate IL-1β stimulation-prompted stem cell-like properties of HNSCC and melanoma cells." (PMID 32547321, 2020). "Moreover, IL-1β stimulation promoted the stem-like capabilities of both HNSCC cells and melanoma cells, including the enrichment of aldehyde dehydrogenase+ (ALDH+) cells, up-regulation of stem cell related markers Nanog, OCT4, and SOX2, sphere formation and chemoresistance." (PMID 32547321, 2020). "Interestingly, when we examined the relationship between MITF/AXL ratio and IL1B using 18 human melanoma cells without drug treatment, we found a strong inverse correlation between the MITF/AXL ratio and IL1B gene expression." (PMID 33396632, 2020). "Moreover, the lack of NLRP1 leads to reduced activity of caspase-1, IL-1β, and NF-κB in various human melanoma cell lines." (PMID 33015196, 2020). "Thus, we determined the expression of known NF-κB targets in melanoma, e.g., MMP9, CCL20 and IL1B." (PMID 32712598, 2020). "Unlike IL-1β, IL-18 is pretty low in melanoma cells, even undetectable." (PMID 28360909, 2017).